GPATCH4 (G-patch domain containing 4 (gene/pseudogene))
Synonyms: GPATC4; FLJ20249; DKFZP434F1735
Gene: Protein-coding gene on chromosome 1 (156,594,301 to 156,601,496, reverse strand). Ensembl gene ENSG00000160818.
Subcellular location (Human Protein Atlas): Nucleoli; Nucleoplasm
Genetic constraint (gnomAD): Loss-of-function variants: 20 observed, 17.25 expected, observed/expected ratio (o/e) 1.16, 90% interval 0.81 to 1.67. The upper end of that interval is the gene's LOEUF score, 1.67, which puts it in group 6 of 6, group 1 being the genes least tolerant of losing a copy. Missense variants: 346 observed, 410.77 expected, observed/expected ratio (o/e) 0.84, 90% interval 0.77 to 0.92. Synonymous variants: 113 observed, 143.14 expected, observed/expected ratio (o/e) 0.79, 90% interval 0.68 to 0.92.
Homologues: Orthologues: chimpanzee GPATCH4 (81% identical), macaque GPATCH4 (75% identical), pig GPATCH4 (64% identical), rabbit GPATCH4 (58% identical), dog GPATCH4 (56% identical), rat Gpatch4 (55% identical), mouse Gpatch4 (52% identical), zebrafish gpatch4 (28% identical), tropical clawed frog gpatch4 (24% identical), Drosophila melanogaster CG15561 (21% identical). Paralogues in human: PINX1 (13% identical).
Diseases named in the same sentence as GPATCH4 in open-access papers:
GPATCH4 is named in the same sentence as 7 diseases in open-access papers, as found by Europe PMC text mining. Sharing a sentence is not in itself a finding about the gene and the disease. The quoted sentences say what the papers report.
glioblastoma (1 paper, 2021). The most malignant astrocytic tumor (WHO grade IV). "Also,ZC3H18,SLIT2 CARF,GPATCH4,CAMK2D,BCORL1,ARHGAP4mutations were found in glioblastoma (T03)." (PMID 34430964, 2021).
hepatocellular carcinoma (1 paper, 2022). A malignant tumor that arises from hepatocytes. "GPATCH4 was identified in melanoma patient sera and was revealed to be increased in hepatocellular carcinoma." (PMID 35884586, 2022).
migraine (1 paper, 2025). "Among these genes, the five most significantly associated with migraine were BBS4 (p = 3.60×10−6), PAM (p = 6.50×10−5), MICA (p = 9.60×10−5), BLM (p = 4.35×10−4), and GPATCH4 (p = 7.29×10−4)." (PMID 41261954, 2025). "For migraine with aura, MICA (p = 2.82×10−7), GPATCH4 (p = 2.39×10−5), BBS4 (p = 7.64×10−4), ALMS1 (p = 8.40×10−4), and CCDC180 (p = 3.38×10−3) were the five most significant ones." (PMID 41261954, 2025). "SMR and INTACT confirmed the validity of BLM, C12orf76, GPATCH4, PAM, SERPINC1 for migraine, and ALMS1, GPATCH4, NCF2, SLC12A1, ZKSCAN8P1 for migraine with aura." (PMID 41261954, 2025). "The results of the SMR, colocalization, and INTACT sensitivity analyses provided further validation of BLM, C12orf76, GPATCH4, PAM, SERPINC1 as contraindicated drugs’ target genes for migraine, and ALMS1, GPATCH4, NCF2, SLC12A1, ZKSCAN8P1 for migraine with aura." (PMID 41261954, 2025).
tumor (4 papers, 2014 to 2023). "In contrast, we observed contradictory effects of LPS including the increased proliferation and expression of several tumor-associated genes and the decreased expression of other cancer-associated genes in tumor enteroids including LOC610994 (Zeta Crystallin), Gpatch4, SLC7A1, ATP13A2, and TEX45." (PMID 35884586, 2022). "While LPS incubation resulted in a pro-cancer gene expression pattern and stimulated proliferation of IBD enteroids and colonoids, downregulation of several cancer-associated genes such as Gpatch4, SLC7A1, ATP13A2, and TEX45 was also observed in tumor enteroids." (PMID 35884586, 2022). "Interestingly, while LPS treatment increased the proliferation and expression of the GEN1, KRIT1, CENPF, CPLANE1, STYK1, and KHDRBS3 genes, it decreased the expression of the cancer associated LOC610994, Gpatch4, SLC7A1, ATP13A2, and TEX45 genes in tumor enteroids." (PMID 35884586, 2022). "Analysis of CHD1L correlated proteins in the tumor tissue revealed that POLR3C, PRKAB2, SETDB1, GPATCH4, and MSTO1 were the top five ones." (PMID 37033447, 2023). "Analysis of RACGAP1 correlated proteins in the tumor tissue revealed that POLR3C, PRKAB2, SETDB1, GPATCH4, and MSTO1 were the top five." (PMID 36430577, 2022).
GPATCH4 also shares sentences with these, for which no sentence is quoted: cancer (2 papers); melanoma (1); migraine with aura (1).